HAND2-AS1 (HAND2 antisense RNA 1)
Synonyms: DEIN; NBLA00301; FLJ11539; UPH
Gene: Long non-coding RNA gene on chromosome 4 (173,521,334 to 173,697,469, forward strand). Ensembl gene ENSG00000237125.
Diseases named in the same sentence as HAND2-AS1 in open-access papers:
HAND2-AS1 is named in the same sentence as 10 diseases in open-access papers, as found by Europe PMC text mining. Sharing a sentence is not in itself a finding about the gene and the disease. The quoted sentences say what the papers report.
cervical cancer (2 papers, 2019 to 2021). A primary or metastatic malignant neoplasm involving the cervix. "In this study, we aimed to investigate the mechanism of HAND2 antisense RNA 1 (HAND2-AS1) on the invasion and metastasis of cervical cancer cells." (PMID 31889905, 2019).
serous ovarian carcinoma (1 paper, 2021). "The known tumor suppressor lncRNA HAND2 Antisense RNA 1 (HAND2-AS1) was identified as one of the differentially expressed lncRNAs in high-grade serous ovarian carcinoma." (PMID 34249094, 2021).
cancer (1 paper, 2023). A tumor composed of atypical neoplastic, often pleomorphic cells that invade other tissues. "The HAND2-AS1 (HAND2 Antisense RNA 1) Long noncoding RNA (lncRNA) has emerged as a participant in the initiation of various cancer types, underscoring its pivotal involvement in both oncological processes and immune responses." (PMID 38042769, 2023).
HAND2-AS1 also shares sentences with these, for which no sentence is quoted: neuroblastoma (3 papers); tumor (2); colorectal cancer (1); infection (1); non-small cell lung carcinoma (1); oral diseases (1); urolithiasis (1).